XRCC5 (X-ray repair cross complementing 5)
Diseases named in the same sentence as XRCC5 in open-access papers (continued):
Sharing a sentence is not in itself a finding about the gene and the disease.
tumor (continued). "In addition, higher XRCC5 expression was correlated with deeper tumor invasion (P = 0.036) and later clinical staging (P = 0.045)." (PMID 30217218, 2018). "Additionally, XRCC5 has been proved to be overexpressed in various tumor tissues (including CRC), which implies that XRCC5 is a tumor promoting factor." (PMID 29049411, 2017). "Nuclear proteins of tumor tissues were exacted, XRCC5 and COX-2 were detected with Western blot." (PMID 29049411, 2017). "Additionally, the combination of STL127705, an inhibitor of the XRCC6/XRCC5 heterodimer, with radiotherapy notably suppressed tumor growth in patient-derived xenograft (PDX) and cell line mouse transplant tumor models, especially in the context of CNOT7 deficiency." (PMID 41249119, 2025). "Mechanistically, DCLK1 bound and phosphorylated XRCC5, which in turn transcriptionally activated cyclooxygenase-2 expression and enhanced prostaglandin E2 production; these events collectively generated the inflammatory tumor microenvironment and enhanced the aggressive behavior of CRC cells." (PMID 35910805, 2022). "Further investigations revealed that knockdown of the TFs candidates—DDB1, PARP1, XRCC5, RPA1, and RPA3—resulted in a significant reduction in tumor sphere formation." (PMID 40230524, 2025). "PRKDC, XRCC6, XRCC5 and PARP1 were significantly downregulated in tumor tissue of mice treated with ESCs and ESC-CM compared with those of mice treated with PBS." (PMID 38654216, 2024). "Among these genes, CDC25C, NEIL3, H2AFX, NBN, XRCC5 and RAD1 were all validated to be upregulated in NSCLC tumor tissues." (PMID 36408135, 2022). "Statistically significant differences were observed in the patients with LUAD in the XRCC5 and XRCC6 groups (P < 0.05), with a positive correlation between the tumor stage and gene expression." (PMID 34486486, 2021). "Our results indicated that the expression levels of XRCC5/6 were positively correlated, while those of XRCC4 were negatively correlated with tumor purity." (PMID 34486486, 2021). "We further evaluated the effect of XRCC5 on COX-2 expression and tumor growth in nude mice with LoVo cell xenografts." (PMID 29049411, 2017). "Moreover, our study provided in vivo evidence that XRCC5 plays an essential role in intestinal tumorigenesis by contributing to COX2 and PGE2 upregulation in tumor tissues." (PMID 35910805, 2022). "Transcriptome analysis suggests the enhanced DSB repair in tumor cells in the OB can be attributed to an increased expression of a group of genes (MRE11, XRCC5, XRCC6 and PRKDC) essential to the NHEJ pathway of DSB repair, which is a critical determinant of radiosensitivity." (PMID 36482431, 2022). "Consistent with the Oncomine analysis, comparison of all available normal (n = 41) and tumor tissues (n = 469) revealed overexpression of XRCC6, XRCC5, PRKDC, XRCC4, and PAXX in tumors compared to normal tissues, while LIG4 and NHEJ1 displayed lower expression in the tumor tissues." (PMID 33195430, 2020). "Interestingly, direct siRNA silencing of XRCC5 enhanced low-dose SASP (0.1mM)-induced PEL apoptosis, potentially due to impaired DNA-damage repair machinery in tumor cells." (PMID 25860939, 2015). "In these previous studies, sets of genes associated with pathways such as apoptosis (e.g., bax, bcl-2), DNA damage repair (e.g., Ku80, GADD45, XRCC5), cell adhesion (e.g., ICAM-3), angiogenesis (e.g., HIF-1a), and tumor cell invasion (e.g., CTSL, CTSB) were identified." (PMID 20184742, 2010). "Immunohistochemistry was performed for tumor and skin tissues according to the standard procedure using the following primary antibodies: XRCC6 (ab92450; Abcam), LIG4 (ab193353; Abcam), PARP1 (ab191217; Abcam), DNA-PK (#38168; Cell Signaling) and XRCC5 (WH0007520M2; Sigma-Aldrich)." (PMID 38654216, 2024). "Furthermore, the overexpression pattern is more robust for XRCC5 as observed in paired normal and tumor tissue comparison, while XRCC6 did not exhibit significant difference." (PMID 33195430, 2020).
tumor (continued). "However, analysis of 41 paired normal and tumor tissues revealed significant overexpression of only XRCC5, PRKDC, and PAXX genes in tumor tissues compared to the normal colon (respectively), while LIG4 and NHEJ1 still displayed reduced expression (respectively)." (PMID 33195430, 2020). "Immunohistochemistry and immunofluorescence analysis showed that CDC25C, H2AFX, NBN, XRCC5 and RAD1 had positive strong expression in NSCLC tumor tissues and negative weak staining in normal lung tissues and mainly distributed in nucleus and cytoplasm." (PMID 36408135, 2022). "Comparison of the methylation levels in LUAD tumor tissues with those in normal tissues identified three relevant methylation sites each in XRCC4 and XRCC5 (P < 0.05), whereas no such methylation sites were found in XRCC6 (P < 0.05)." (PMID 34486486, 2021). "Also, CDKN2A and XRCC5, which are TSGs involved in DNA repair, displayed high hypermethylation intensities and, unlike MLH1, were altered in all tumor types." (PMID 28581523, 2017). "In addition, multivariate Cox analysis demonstrated that the tumor stage, XRCC4, XRCC5, and XRCC6 could predict the tumor prognosis independent of other factors for the OS in patients with LUAD (P < 0.05)." (PMID 34486486, 2021).
cancer (79 papers, 2003 to 2026). A tumor composed of atypical neoplastic, often pleomorphic cells that invade other tissues. "Previous studies have shown that abnormal expression of XRCC5 is associated with increased risk of cancer." (PMID 32501811, 2020). "XRCC5, which encodes the Ku80 subunit of the Ku heterodimer involved in DNA double strand break repair and has been associated with cancer development, was further analyzed in the MTC cohort." (PMID 26870890, 2016). "Previously, SNPs in XRCC5 have been shown to influence cancer risk and chromosomal radiosensitivity." (PMID 28324443, 2014). "Additionally, the effect of the XRCC5 rs1051685 AG genotype implicates DNA repair fidelity and apoptosis regulation in cancer risk modulation, where efficient DNA repair and controlled cell death prevent malignant transformation." (PMID 39457514, 2024). "Further studies are needed to clarify the impact of XRCC5 gene polymorphisms on cancer risk in LS." (PMID 39457514, 2024). "However, mice with homozygous defects in Xrcc5 have a slightly earlier onset of cancer and, in humans, a rare microsatellite polymorphism in Ku80 is associated with cancer of varying radiosensitivity." (PMID 37407587, 2023). "The results confirmed the association of PC4 with XRCC5/XRCC6 in relevant cancer and normal cells." (PMID 37437887, 2023). "The XRCC5 rs828907 -1401G>T is located in the promoter region, what may affect gene expression, and has been linked to increased cancer susceptibility in the Asian population." (PMID 37894339, 2023). "Studies pertaining to this predicted that this VNTR polymorphism, which includes a variable number of Sp1-binding motifs, that might be influencing the transcriptional activity of XRCC5, which lead to a phenotypic variation that could affect susceptibility to cancer." (PMID 33685509, 2021). "Here we find that melatonin (MT) not only downregulates TRIP13 but also the DNA repair proteins RAD51 and XRCC5, thereby inhibiting aberrant DNA repair in cancer cells." (PMID 41145438, 2025). "LSVH with the XRCC5 rs1051685 heterozygous (AG) genotype were less likely to develop cancer at a younger age than those with the wild-type (AA) genotype, with a 31% estimated reduction in risk (Adj HR: 0.69 [CI, 0.48–0.99], p = 0.043)." (PMID 39457514, 2024). "LSVH who were heterozygous for the XRCC5 rs1051685 SNP showed significant protection against younger age at cancer diagnosis (Adj HR: 0.69 [CI, 0.48–0.99], p = 0.043)." (PMID 39457514, 2024). "Kaplan–Meier survival analysis also showed a significant difference in age at cancer diagnosis between genotypes of XRCC5 rs1051685 SNP (comparing AA, AG, and GG; log-rank test p = 0.040)." (PMID 39457514, 2024). "XRCC5 was originally reported to repair double-strand breaks in DNA; thus, it was considered to fuel therapeutic resistance to DNA-damaging agents in cancer 56-64." (PMID 35910805, 2022). "DNA polymorphism such as studies on single nucleotide polymorphisms (SNPs) and variable number of tandem repeats (VNTRs) at NHEJ repair genes (XRCC5, XRCC6 and XRCC7) are associated with an increased risk of radiation sensitivity and cancer." (PMID 33685509, 2021). "ClC-3 is regulated by X-ray repair cross-complementing 5(XRCC5), which binds to its promoter, inducing cancer cell proliferation, migration, and invasion through the transforming growth factor-β (TGF-β)/Smad signaling pathway." (PMID 34778915, 2021). "Altered activities of NHEJ genes including XRCC5/KU80, XRCC6/KU70, PRKDC/DNA-PKcs, and TP53BP1 can be either negatively or positively associated with platinum resistance, depending on types of cancer cell lines or clinical samples." (PMID 34645978, 2021). "Polymorphisms of MLH1, APEX1, MUTYH, OGG1, NUDT1, and XRCC5 are associated with sporadic CRC and other site‐specific cancers." (PMID 29664240, 2018). "The exact roles of XRCC5 in preventing normal cell from canceration and participating in the progression of cancer cells need to be evaluated with more studies." (PMID 29049411, 2017).
cancer (continued). "It is known that COX-2 plays a role in promoting cancer cell growth, and our results showed that XRCC5 bound to the promoter of COX-2 to up-regulate its expression." (PMID 29049411, 2017). "The other important genes in this pathway like Abl1, Gml, Brca1, Zak, Xrcc5, Trex1, Pms1, Ccnu and Apex2 were also up regulated in the cancer cells." (PMID 22321936, 2012). "Additionally, the heterozygous genotype for XRCC5 rs1051685 SNP appears to delay the onset of cancer in this population." (PMID 39457514, 2024). "Interestingly, the XRCC5 rs1051685 heterozygous AG genotype significantly conferred a protective effect against young age at cancer diagnosis, contradicting previously reported results." (PMID 39457514, 2024). "In the current study, we used mass spectrometry to analyze proteins that can bind to LINC01419; the XRCC5 (Ku80) caught our attention, because it is known to DNA damage repair in various cancers, and then, the direct binding of LINC01419 to XRCC5 was determined." (PMID 35903292, 2022). "XRCC5 overexpression makes cancer cells resistant to standard chemotherapy." (PMID 36143471, 2022). "So that it is worth to pay more attention to explore the role of XRCC5 gene in variety cancers." (PMID 27852033, 2016). "The discrepancies between our results and previously reported findings on the influence of GSTT1 null and XRCC5 rs1051685 SNP on the age at cancer diagnosis could be due to genetic heterogeneity among LS cohorts, different ethnicities, and varying sample sizes." (PMID 39457514, 2024). "This is also the first report demonstrating the association of MRE11 rs2155209, XRCC5 rs828907, LIG4 rs1805388, ATM rs1801516 and RAD51 rs12593359 with survival in HNSCC, as well as the first to indicate that CHEK1 rs558351 may play a role in cancer disease." (PMID 37894339, 2023). "However, the knowledge about the function of XRCC5 in cancer development is changing over time." (PMID 29049411, 2017). "The XRCC5 rs1051685 heterozygous (AG) and GSTT1 null genotypes conferred a protective effect that delayed age at cancer diagnosis in LS." (PMID 39457514, 2024). "To confirm the versatility of our findings across various cancer cells, we performed additional analyses and found that the DCLK1/XRCC5/COX2 axis is conserved in many types of solid cancer cell lines including breast, lung and pancreatic cell lines." (PMID 35910805, 2022). "Curcumin sensitized cancer cells to IR by altering the expression of DNA repair-related genes, including DNA ligase IV (LIG4), X-ray repair cross complementing 5 (XRCC5) and polynucleotide kinase/phosphatase (PNK)." (PMID 34572726, 2021). "Upon UV exposure, interaction of FOXL2 with both XRCC5 and XRCC6 was significantly diminished in KGN cells, and this effect was consistently observed in other types of cancer cells." (PMID 32332759, 2020). "We found, for instance, that 6 cancer-related targets changed their expression levels: HSPD1, PARP1, XRCC5, PRDX2, MTA2 and FASN." (PMID 24801752, 2014). "Firstly, we evaluated the mRNA expression of six DDR-related genes in NSCLC tissues in GEPIA, which demonstrated that CDC25C, NEIL3, H2AFX, NBN, XRCC5 and RAD1 were all significantly higher expressed in NSCLC cancer tissues compared to with normal lung tissues." (PMID 36408135, 2022). "The role the 3-M proteins have on XRCC5 function and DNA damage response is not characterised; however, there is evidence that elevated expression of CUL7 is associated with cancer progression and poor survival." (PMID 24711643, 2014). "Thus, our work is the first to draw attention to its possible impact on cancer survival and may be of additional clinical relevance in HNC as the data indicate a potential predictive role of XRCC5 in immunotherapy combined with RT." (PMID 37894339, 2023).
infection (14 papers, 2010 to 2024). The state of being infected such as from the introduction of a foreign agent such as serum, vaccine, antigenic substance or organism. "We found the production of Cxcl10 and Il-6 was strongly impaired in cells lacking Prkdc−/− or Xrcc5−/− during MVA infection whereas the response of these cells to infection by Newcastle disease virus (NDV, an RNA virus) remained intact." (PMID 23251783, 2012).
XRCC5 also shares sentences with these, for which no sentence is quoted: cervical carcinoma (8 papers); adenocarcinoma (5); viral infection (5); glioblastoma (4); pancreatic cancer (4); triple-negative breast carcinoma (4); autoimmune disease (3); B cell lymphoma (3); diabetes mellitus (3); head and neck cancer (3); lymphoma (3); nasopharyngeal carcinoma (3); severe combined immunodeficiency (3); atherosclerosis (2); esophageal cancer (2); multiple myeloma (2); neurodegenerative disease (2); pancreatic ductal adenocarcinoma (2); pneumonitis (2); respiratory diseases (2); sarcoma (2); squamous cell carcinoma (2); acute lymphoblastic leukemia (1); acute myeloid leukemia (1); adenocarcinoma of the cervix (1); adenocarcinomas of the esophagus (1); amyotrophic lateral sclerosis (1); B cell deficiency (1); bronchiectasis (1); carcinoma in situ (1).
A further 42 diseases each share a sentence with XRCC5 in 1 paper.